MTOR (mechanistic target of rapamycin kinase)
Diseases named in the same sentence as MTOR in open-access papers (continued):
Sharing a sentence is not in itself a finding about the gene and the disease.
breast cancer (continued). "Combination treatments inhibit the proliferation, invasion and migration of 4T1 and MDA-MB-231 breast cancer cells by down-regulating AKT/mTOR signaling pathway." (PMID 34282830, 2022). "CDK4/6I phosphorylate AKT via PDK1 to activate PI3K/AKT/mTOR pathways in ribociclib-resistant breast cancer cells." (PMID 36358806, 2022). "Studies in breast cancer cells demonstrate that SALL2 silencing induced the AKT/mTOR pathway activation via the downregulation of PTEN." (PMID 36438565, 2022). "PI3K/mTOR inhibitors were shown to upregulate Bcl-2 levels in MCF-7 breast cancer cells and synergize with the BH3 mimetics ABT-737 and ABT-199." (PMID 35053443, 2022). "CLE-10, a Carpesium abrotanoides-derived compound, induces apoptosis and autophagy of breast cancer cells by inactivating PI3K/AKT/mTOR." (PMID 36139919, 2022). "A more promising approach uses the small-molecule tyrphostin, NT157 to target IRS; this method downregulates IRS protein expression and sensitizes ERα+ breast cancer cells to the mammalian target of rapamycin (mTOR) inhibitor, rapamycin." (PMID 35846378, 2022). "Other prominent STIs that emerged in breast cancer treatment include everolimus, a second-generation inhibitor of the Mammalian Target of Rapamycin (mTOR), and inhibitors of Cyclin-Dependent Kinases (CDKs)." (PMID 35626053, 2022). "Genes in the phosphatidylinositol 3-kinase/AKT/mammalian target of rapamycin (mTOR) pathway are highly expressed in breast cancer and are related to prognosis." (PMID 35608730, 2022). "miR-424-5p is a potential tumour suppressor gene that inhibits the development of breast cancer cells by regulating autophagy mediated by the PTEN/PI3K/AKT/mTOR pathway." (PMID 35883139, 2022). "This suppression of mTOR is being investigated in various models as a potential treatment for breast cancer." (PMID 36497303, 2022). "The clinical development of PI3K/AKT/mTOR targeted therapies for breast cancer treatment and the increasing appreciation that PI3K/AKT/mTOR contributes to endocrine resistance emphasises the relevance of studying the pathway in cell line or PDO models." (PMID 36045910, 2022). "For instance, transient elevation of phosphorylated AMPK and reduction in phosphorylated mTOR induce autophagy in breast cancer cells." (PMID 36251949, 2022). "HER2 overexpression results in abnormal activation of the RAF/MEK/ERK and PI3K/AKT/mTOR signaling pathways in breast cancer." (PMID 36539659, 2022). "For instance, mTOR activation was reported to promote lapatinib resistance in breast cancers; mTOR modulates gemcitabine resistance in lung cancer through mTORC2." (PMID 36214762, 2022). "Based on these results, we propose mTOR inhibitors in combination with CDK4/6 inhibitors as a potential therapeutic strategy in ER+HER2− breast cancers with S6K1 amplification." (PMID 36042494, 2022). "Given these insights, it appears likely that mTOR signalling is critical for BRCA1 responsiveness to DNA damage and therefore that BRCA1-negative breast cancer cells are more responsive to pan-mTOR inhibition." (PMID 36428613, 2022). "Our results suggest that in breast cancer cells, GATA3 loss-of-function (via genetic alterations or other mechanisms) activates the PI3K/Akt/mTOR pathway and leads to resistance to apoptosis." (PMID 35440675, 2022). "In fact, miR-451a reduces Akt and mTOR phosphorylation, leading to anti-proliferative and pro-apoptotic activity in breast cancer cells." (PMID 35309939, 2022). "Accumulating evidence has demonstrated the functions of p-AKT and p-mTOR in promoting the progression of breast cancer and gastric cancer." (PMID 36060798, 2022). "This study aims to investigate the anti-cancer effects of andrographolide in breast cancer cells by evaluating cell viability and apoptosis as well as its underlying mechanisms through estrogen receptor (ER)-dependent and PI3K/AKT/mTOR signaling pathways." (PMID 35684480, 2022).
breast cancer (continued). "At cellular and molecular level, breast cancer is regulated by signaling pathways among which mammalian target of rapamycin (mTOR) is a prominent one." (PMID 35795855, 2022). "The breast cancer pathway and mammalian target of rapamycin (mTOR) signaling pathway were the most correlated pathways in the KEGG analysis." (PMID 35438526, 2022). "LHX6 is associated with many kinds of cancers and can inhibit the proliferation, invasion, and migration of breast cancer cells by modulating the PI3K/Akt/mTOR and Wnt/β-catenin signaling pathways." (PMID 35203526, 2022). "Clinical trials have shown that mTOR inhibitors can improve ER+ or HER2+ breast cancer patient outcome but failed in TNBC patients, possibly due to a distinct activation of mTOR." (PMID 35963851, 2022). "Mechanistic studies revealed that MiDs regulated mitochondrial fission via inhibiting the Akt-mTOR pathway and that dysregulated miR-34a-3p can target and manipulate MiDs in breast cancer cells." (PMID 36192752, 2022). "Here, we illustrate the use of iLINCS in detecting and modulating aberrant mTOR pathway signaling, analysis of proteogenomic signatures in breast cancer and in search for COVID-19 therapeutics." (PMID 35945222, 2022). "Taken together, we deduced that deglycosylated EpCAM promote autophagy via PI3K/AKT/mTOR signaling pathway in breast cancer cells." (PMID 34983878, 2022). "Studies have found that clinically, small molecule inhibitors can inhibit the PI3K/AKT/mTOR signaling pathway and inhibit the occurrence of autophagy, to treat breast cancer." (PMID 35813295, 2022). "In vitro, SCA induced autophagy in breast cancer cells via the PI3K–Akt–mTOR pathway and decreased the Bcl-2/Bax ratio to induce apoptosis in breast cancer cells." (PMID 36408240, 2022). "Our results show metastasis-specific mutations in a number of pathways and cancer types, including the MAPK, CDK, PIK/AKR/mTOR, and other pathways in breast cancer patients." (PMID 36507516, 2022). "The transcriptional suppression of negative regulators of mTOR is intrinsic in luminal‐like breast cancer cells, leading to the development of CSC‐like properties." (PMID 36226253, 2022). "Our previous report indicated that PROCR concomitantly activates multiple pathways including ERK, PI3K–Akt–mTOR, and RhoA–Rock–P38 signaling in breast cancer cells." (PMID 35285801, 2022). "Alterations and hyperactivation of the PI3K/AKT/mTOR pathway are observed in many cancers, with estimations that aberrations are present in 60–70% of breast cancers." (PMID 36045910, 2022). "Breast cancer apoptosis was significantly increased with 25–50 μg/ml concentration of extract as compared to control, whereas the level of mTOR was effectively reduced by the flavonoids." (PMID 35795855, 2022). "Regulation of the PI3K/Akt/mTOR signaling pathway was found to mediate this anti-breast cancer potential." (PMID 35795855, 2022). "We highlight one example from our prediction results: our model obtained AUROC of 0.9 ± 0.001 for predicting sensitivity to everolimus, an immunosuppressive drug of type mTOR inhibitor, screened for breast cancer patients in our data." (PMID 36168036, 2022). "Anti-estrogens and other agents used in ER+ breast cancer treatment such as PI3K/mTOR inhibitors and chemotherapeutics have been reported to upregulate Bcl-2 proteins, priming the cell for BH3 mimetic activity." (PMID 35053443, 2022). "Some of these pathways, such as the PI3K/AKT, MAPK, and mTOR signaling pathways, are the targets of therapeutics approved for treatment of breast cancer patients (e.g. rapamycin )." (PMID 35614362, 2022).
breast cancer (continued). "PI3K/AKT/mTOR inhibitory agents that have been studied in literature, such as rapamycin and everolimus, which both inhibit mTOR, are expected to lead to better therapeutic responses compared to traditional treatment modalities in primary breast cancers." (PMID 36507516, 2022). "Breast cancer mutations also appear in receptor tyrosine kinase receptors, such as HER2, and phosphorylation of this receptor leads to PI3K/Akt/mTOR activation." (PMID 35610639, 2022). "On the other hand, mutation in PIK3CA, a gene that is ubiquitously expressed in fat and implicated in breast cancer, alters the PI3K/AKT/mTOR pathway by activating the pathway." (PMID 35682652, 2022). "The EGFR pathway activated by EREG and the PI3K/Akt/mTOR pathway activated by FGF10 are well known to be part of the mechanisms of resistance to HER2-targeted therapy in HER2-positive breast cancer." (PMID 35954313, 2022). "In a screen of breast cancer cell lines, PTEN, Akt, and phosphorylated ribosomal S6 kinase 1 (pS6K1) levels were associated with sensitivity to the mTOR inhibitor, rapamycin." (PMID 36046843, 2022). "One of the key drivers of Mcl-1 upregulation in breast cancer cells is the activation of PI3K/mTOR signaling." (PMID 35053443, 2022). "The suppression of mTOR is being explored in various models as a possible treatment for breast cancer." (PMID 36497303, 2022). "Ononin has an anti-inflammatory effect on lipopolysaccharide (LPS)-induced inflammation, and reported to inhibit proliferation of breast cancer cells via PI3K/AKT/mTOR signaling pathway." (PMID 35922850, 2022). "The PI3K/Akt/mTOR signaling pathway has a major role in essential cellular activities, such as cell proliferation and apoptosis, and is often deregulated in breast cancer." (PMID 35784555, 2022). "MTOR was upregulated in numerous tumors, such as ovarian cancer, breast cancer, lung cancer, and so on." (PMID 36211008, 2022). "Everolimus (ZINC169677008) is one of the mTOR inhibitors and has been approved for the treatment of multiple cancers such as breast cancer and renal cell carcinoma." (PMID 35450397, 2022). "Enforced expression of HOXD8 in breast cancer repressed tumor growth by inactivating AKT/mTOR pathway." (PMID 36387262, 2022). "Breast cancer is associated with upregulation of HER-2 levels and activation of PI3K/AKT, which leads to increased stability of HIF-1 via mTOR." (PMID 36059650, 2022). "ERBB2 mutations were identified in 5/41 CDK4/6-resistant tumor, and preclinical work demonstrated that ERBB2 mutation activates downstream MAPK/AKT/mTOR and confers resistance to CDK4/6 blockade in breast cancer cells." (PMID 35804935, 2022). "Here, we utilized gene expression signatures from 9 ER+ breast cancer cell lines and 23 patients treated with everolimus to develop and validate an integrative machine learning biomarker of mTOR inhibitor response." (PMID 36304922, 2022). "In this review, we describe the multiple agents that target the PI3K/Akt/mTOR pathway which has and is being evaluated in the clinic for the treatment of breast cancer but with variable success." (PMID 36046843, 2022). "The PI3K-Akt-mTOR pathway is a viable target for cancer treatment and can be used to treat various malignant tumours, including follicular lymphoma and breast cancer." (PMID 35614940, 2022). "Among these mechanisms, targeting the mTOR signaling pathway in breast cancer was identified as a potential means for overcoming chemoresistance." (PMID 35795855, 2022). "Mechanistically, through stabilizing CDCA5, TPI1 activates PI3K/AKT/mTOR pathway, which in turn promotes breast cancer metastasis and glycolysis." (PMID 35509067, 2022). "Previous studies have demonstrated that SLC7A5 regulates AKT/mTOR pathway expression in breast cancer." (PMID 35986300, 2022).
breast cancer (continued). "In brief, genes involved in the PI3K/Akt/mTOR pathway, which has a role in endocrine sensitivity and breast cancer survival, show lower expression in ultralow risk tumors, as observed both by the multigene module AKT/mTOR and on the single‐gene level." (PMID 35179782, 2022). "Literatures have shown that mTOR is a critical signaling pathway involved in the pathophysiology of breast cancer and flavonoids due to its interfering potential with these mTOR cascades have shown them targeting candidates for breast cancer therapy." (PMID 35795855, 2022). "In breast cancer cells, overexpressed miR-29a-3p promotes the repression of HIF1α (hypoxia-inducible factor 1 subunit alpha) protein, the downstream mTOR effector." (PMID 36430972, 2022). "An optimal level of GREB1 expression is necessary for the proliferation of breast cancer cells through PI3K/Akt/mTOR pathway signaling." (PMID 36555156, 2022). "UA has been shown to induce apoptosis and antimetastatic activity by destructing the PI3K/Akt/mTOR signaling pathways in human chronic myelogenous leukemia and breast cancer." (PMID 36613808, 2022). "Research studying flavonoid molecular docking has probed for an effective inhibitor against mTOR in breast cancer." (PMID 35795855, 2022). "Phosphoinositide 3-kinase (PI3K)/protein kinase (AKT)/mammalian target of rapamycin (mTOR) signaling pathway, referred to as PI3K/AKT pathway, is one of the most frequently activated pathogenic signaling cascades in breast cancer." (PMID 35311116, 2022). "The key words searched in our article were “Cancer”, “breast cancer”, “flavonoids”, “mTOR signaling”, and “chemo resistant breast cancer”." (PMID 35795855, 2022). "In this respect, inhibition of DPP4 has been reported to accelerate EMT and breast cancer metastasis via CXCL12/CXCR4/mammalian target of rapamycin (mTOR) signaling." (PMID 35053615, 2022). "WDR5 inhibition or degradation suppresses translation and growth of breast cancer cells, alone or in combination with mTOR inhibitors." (PMID 36043466, 2022). "Everolimus, an inhibitor of the mammalian target of rapamycin (mTOR), is used not only for treating inoperable or recurrent breast cancer but also for suppressing rejection in organ transplantation and for the treatment of tuberous sclerosis complex." (PMID 36188563, 2022). "Since mTORC1 regulates eIF4E abundance through 4EBP1 phosphorylation, thus, there exist an intriguing possibility of a positive feedback interaction between polyamines and mTOR pathway in regulating breast cancer cells growth." (PMID 36135836, 2022). "In summary, multiple mechanisms of resistance and several putative biomarkers have been identified for PI3K and mTOR inhibitors in breast cancer, mostly focusing on specific genetic alterations." (PMID 36046843, 2022). "Endometrial cancer had the leading mutation frequency by integrated analysis of the 8-gene signature in mTOR pathway, followed by breast cancer and melanoma." (PMID 35642038, 2022). "As reported, miR-100-5p inhibits angiogenesis by suppressing mTOR/HIF-1α/VEGF signaling in breast cancer cells, which was also validated in the endothelial cells in the present study." (PMID 35241153, 2022). "This article covered all the studies related to flavonoids targeting the mTOR signaling cascades in breast cancer." (PMID 35795855, 2022). "In vivo, the PI3K/Akt/mTOR signaling pathway generated by caveolin-1 activation increased breast cancer movement, invadopodia development, and metastasis." (PMID 35682652, 2022). "The use of mTOR inhibitors such as everolimus has shown promising results in improving outcomes of ER+/HER2- breast cancer patients." (PMID 36304922, 2022). "It inhibited the phosphorylation of Akt, mechanistic target of rapamycin (mTOR), rS6, and ErbB3 binding protein 1 in breast cancer cells, suggesting a link between the Akt/mTOR signaling pathway and mitochondrial function in the context of breast cancer." (PMID 35223475, 2022).
breast cancer (continued). "In this study, we demonstrated that the mTOR signalling pathway is regulated by the expression level of MED16 in ER+ breast cancer." (PMID 36294896, 2022). "To test this, we first examined the effect of SCA on PI3K–Akt–mTOR signaling-related proteins in breast cancer cells." (PMID 36408240, 2022). "Specifically, it induced excessive autophagy in breast cancer cells by inhibiting the PI3K–Akt–mTOR signaling pathway, ultimately leading to cell apoptosis." (PMID 36408240, 2022). "LncRNA regulates breast cancer endocrine therapy resistance: LncRNA-UCA1 mediates Wnt / β-Catenin and AKT / mTOR signaling pathway promotes breast cancer endocrine therapy resistant." (PMID 35657638, 2022). "OGN can reverse EMT through the PI3K/Akt/mTOR pathway in breast cancer, and reduce the expression of ZEB-1 through the EGFR/Akt signaling pathway in colon cancer to inhibit EMT." (PMID 35513835, 2022). "The PI3K/AKT/mTOR pathway is a key pathway that involves several intracellular functions of breast cancer, including cell cycle progression and cell growth." (PMID 35684480, 2022). "For example, tanshinone IIA, a Salvia miltiorrhiza Bunge-derived bioactive compound, suppresses proliferation and induces autophagy of breast cancer cells by inactivating PI3K/AKT/mTOR signaling." (PMID 36139919, 2022). "Rationale: PI3K/mTOR signaling is frequently upregulated in breast cancer making inhibitors of this pathway highly promising anticancer drugs." (PMID 35673573, 2022). "Further research supported these findings and indicated that PI3K/mTOR inhibition induced breast cancer cell apoptosis, thereby preventing the emergence of hormone-independent cells." (PMID 35053443, 2022). "The findings showed that in breast cancer tissues (p = 0.0018), ductal tumors (p = 0.0014), in higher grade tumors (grade 2 vs. 3, p = 0.047) a higher expression of mTOR was identified and was related to a low overall survival (p = 0.01)." (PMID 36428613, 2022). "Based on the expression of NPC1 in breast cancer and its known roles in cholesterol metabolism and mTOR signaling pathways, we sought to determine if NPC1 supports tumor-promoting characteristics in vitro." (PMID 35884604, 2022). "For example, some autophagy inducers, such as rapamycin and its derivatives, can block MTOR-cascade-dependent cell growth via cell cycle arrest in MDA-MB-231 breast cancer cells." (PMID 36497321, 2022). "Akt inhibitor has been used in treating ER/PR-positive breast cancer to disrupt the function of the PI3K/Akt/mTOR pathway and alleviate endocrine resistance." (PMID 36293372, 2022). "Race and clinicopathological variables of breast cancer should be considered in studying the prognosis and endocrine therapy resistance related to mTOR pathway genes." (PMID 35608730, 2022). "Transforming growth factor (TGF)-β1 overexpression activates PI3K/AKT/mTOR in breast cancer and increases the resistance potential to chemotherapy." (PMID 36139919, 2022). "To date, only one clinical trial with any mTOR inhibitor has reported genomic information from breast cancer patients before and after treatment." (PMID 36304922, 2022). "mTOR regulates cellular proliferation and growth, and the PI3K-AKT-mTOR pathway is dysregulated in several cancers including breast cancer." (PMID 36536390, 2022). "The PI3K/AKT/mTOR signaling has been shown to involve in cell differentiation, proliferation, anti-apoptosis in breast cancer cells, and oxidative stress and angiogenesis." (PMID 35322748, 2022). "Everolimus, a drug that targets and inhibits the mTOR complex has been shown to improve clinical outcomes in metastatic ER+ breast cancers." (PMID 36304922, 2022).